ZNF594 (zinc finger protein 594)
Description:
May be involved in transcriptional regulation.
Synonyms: KIAA1871
Tractability: PROTAC: ubiquitination databases record sites on it.
Gene: Protein-coding gene on chromosome 17 (5,179,535 to 5,191,868, reverse strand). Ensembl gene ENSG00000180626.
Subcellular location: Nucleus
Subcellular location (Human Protein Atlas): Nucleoplasm
Gene Ontology:
Molecular function: transcription cis-regulatory region binding
Biological process: regulation of transcription by RNA polymerase II
Cellular component: nucleoplasm; nucleus
Genetic constraint (gnomAD): Loss-of-function variants: 0 observed, 0.39 expected, observed/expected ratio (o/e) 0, 90% interval 0 to 1.85. That is too few expected variants to judge how well the gene tolerates losing a copy. Missense variants: 1,037 observed, 1,001 expected, observed/expected ratio (o/e) 1.04, 90% interval 0.98 to 1.09. Synonymous variants: 336 observed, 319.82 expected, observed/expected ratio (o/e) 1.05, 90% interval 0.96 to 1.15.
Homologues: Orthologues: pig ZNF594 (58% identical), zebrafish zgc:66472 (14% identical), Drosophila melanogaster mld (14% identical). Paralogues in human: ZNF91 (43% identical), ZNF160 (40% identical), ZNF84 (40% identical), ZNF208 (40% identical), ZNF420 (40% identical), ZNF107 (40% identical), ZNF729 (40% identical), ZNF184 (38% identical), ZNF99 (38% identical), ZNF347 (37% identical), ZNF473 (36% identical), ZNF845 (36% identical), and 24 more.
Diseases named in the same sentence as ZNF594 in open-access papers:
ZNF594 is named in the same sentence as 1 disease in open-access papers, as found by Europe PMC text mining. Sharing a sentence is not in itself a finding about the gene and the disease. The quoted sentences say what the papers report.
asthma (1 paper, 2022). "Previous studies have suggested that the ZNF594 gene is associated with airway remodeling in asthma, which is characterized by the thickening of the reticular basement membrane (RBM) and regulated through DNA transcription." (PMID 36292752, 2022). "Another study speculated that ZNF594 might be a crucial gene in human primary bronchial epithelial cells, which could impact the effectiveness of inhaled 2-adrenoceptor agonists in managing asthma." (PMID 36292752, 2022).